EPO (erythropoietin)
Diseases named in the same sentence as EPO in open-access papers (continued):
Sharing a sentence is not in itself a finding about the gene and the disease.
anemia (continued). "Furthermore, numerous studies have demonstrated that erythropoietin-stimulating agent (ESA) therapy for anemia in CKD improves quality of life in terms of health." (PMID 37893506, 2023). "In severe anemia, the levels of blood serum EPO increase compared with the normal range." (PMID 38029231, 2023). "Along with increased inflammation and impaired production of erythropoietin, this mechanism may contribute significantly to anemia of CKD." (PMID 35905974, 2023). "In addition, serum soluble Fas (sFas) levels are related to anemia and erythropoietin (EPO) resistance." (PMID 37390095, 2023). "Anemia in men with hypogonadism is partly attributed to declining testosterone levels in aging hypogonadal men and partly due to the effects of testosterone on erythropoietin and erythroid progenitor cells." (PMID 36876281, 2023). "Hypogonadism was significantly linked to advanced age, anemia, and absence of treatment by erythropoietin." (PMID 38282781, 2023). "Recent evidence indicates that EPO and iron are required for ROS generation in erythroblasts, and that ROS are necessary for terminal erythropoiesis while unchecked ROS accumulation results in anemia." (PMID 38153418, 2023). "Even though EPO has been widely applied in preterm infants to prevent anemia, to treat preterm ICH the optimal dose protocol and course as well as the gestational age of the preterm infants need to be investigated further because EPO treatment has shown gestational age-related differences." (PMID 36397619, 2023). "The anti-EPO antibodies may have cross-reacted with endogenous erythropoietin, suppressing its biological functions and subsequently worsening the patients’ anaemia." (PMID 36989322, 2023). "Due to diabetes mellitus, nephropathy may occur, which further undermines renal production of erythropoietin, contributing to anemia." (PMID 37627906, 2023). "The associations of RDW with markers of VC and CVD might be attributed to shortened RBC life span, inhibited erythropoietin response, anemia and impaired iron metabolism." (PMID 36837922, 2023). "HIF-PHIs increase endogenous erythropoietin production and red blood cell production, which can improve the symptoms of anaemia without posing the risks associated with exogenous erythropoietin." (PMID 37623232, 2023). "The point is that if the oral mass cannot be treated, alternative treatments should be performed for these dogs such as blood transfusion in severe anemia cases, parenteral iron therapy, and the administration of recombinant human erythropoietin in mild to moderate anemic dogs." (PMID 37009523, 2023). "Finally, it was demonstrated that, experimentally, Cd suppressed renal erythropoietin (EPO) production through a direct effect and destruction of EPO-producing cells, driving anemia in Cd toxicity." (PMID 37367879, 2023). "EPO was initially proposed as a treatment for anemia secondary to renal failure." (PMID 37298597, 2023). "In cases of genetic hemochromatosis or iron overload without anemia caused by immunosuppressant drug use, obesity, or prior use of iron replacement, phlebotomy or erythropoietin can be a treatment option." (PMID 36650247, 2023). "Anemia in CKD is primarily due to insufficient endogenous erythropoietin production." (PMID 37840653, 2023). "Anemia in pregnancy and the puerperium should be treated according to a staged regimen, administering either iron alone or in combination with an off-label use of human recombinant erythropoietin in selected patients." (PMID 37435001, 2023). "Laboratory evidence of anemia that does not respond to iron or erythropoietin therapy suggests deficiencies in other micronutrients, like copper, zinc, and vitamin B12." (PMID 37606426, 2023). "When EPO levels are increased, the response mechanisms to anemia may have already reached a supraphysiologic threshold of stimulation, as demonstrated by the observed expansion of erythropoiesis in BM evaluation at diagnosis in these cases." (PMID 36574201, 2023).
anemia (continued). "Another approach to improving the condition of anemia in this model is expressing cytokines erythropoietin and IL-3 via knock-in or hydrodynamic injection of DNA plasmids as previously reported for increased reconstitution and development of human erythrocytes." (PMID 37868989, 2023). "Regarding medications, almost all participants from the North/Northeast (97%) with anemia had a prescription of erythropoietin for more than 50% of the assessed time, a number markedly higher than the 53% of the South, 77% of the Southeast, and 71% of the Midwest." (PMID 37395543, 2023). "Ongoing intramedullar hemolysis, marrow suppression from IUT, erythropoietin (EPO) deficiency, and direct inhibitory effect of anti-D on erythroid progenitors have been discussed as causative mechanisms of late hyporegenerative anemia." (PMID 37124190, 2023). "A total of 286 patients had anemia without a clear etiology, of which 182 were excluded due to a lack of EPO data, and an additional 19 were excluded due to loss to follow-up within 2 years." (PMID 37741889, 2023). "Typically, the lowest rate of correct responses in the control group concerned the management of anemia in patients with chronic kidney failure experiencing some trouble with iron supplements, erythropoietin, and situations with hemoglobin levels greater than 11 g/dL and high ferritin." (PMID 38039068, 2023). "The findings suggest that, among the different comorbidities such as oxidative stress and inflammatory stress, erythropoietin-resistant anemia, intradialytic hypotension, muscle weakness, myalgia, etc., are considered as the most significant onset symptoms in CKD or hemodialysis patients." (PMID 36836532, 2023). "Also, younger age and the presence of anti-EPO antibodies in sera related to the development of anaemia in pregnant women with P. falciparum malaria." (PMID 36989322, 2023). "P. falciparum parasite density and younger age could stimulate the production of anti-EPO antibodies, and the antibodies may contribute to the development of malaria-induced anaemia in pregnancy." (PMID 36989322, 2023). "Low serum Cu aggravated anemia in TDT patients by reducing erythropoietin." (PMID 36677007, 2023). "In addition, platinum drugs can cause kidney damage, which can reduce the secretion of erythropoietin (EPO) and further aggravate anemia." (PMID 37777739, 2023). "Anemia of bone marrow diseases showed elevated EPO, probably due to an impaired response to EPO in the bone marrow, which in turn may leads to the production of more EPO." (PMID 37741889, 2023). "Long-term use of tacrolimus, cyclosporine A, ACEI, ARB in MN patients with persistent unalleviated urinary protein would also lead to chronic fibrosis of renal tubules and the interstitium or EPO resistance and would eventually make anemia in these MN patients difficult to treat." (PMID 36799117, 2023). "The presence of anti-EPO antibodies may be related to the development of anaemia in disease conditions such as malaria, HIV/AIDS and systemic lupus erythematosus (SLE)." (PMID 36989322, 2023). "Most researchers agree that expanding the clinical application of RDW to include erythrocyte fragmentation, poor nutritional status, hypertension, dyslipidemia, and erythropoietin abnormalities is more appropriate than restricting the traditional application of RDW to the early detection of anemia." (PMID 37064043, 2023). "The possible changes during pregnancy, and especially in the presence of infections may trigger immune responses including induction of autoimmune-mediated antibodies such as anti-EPO which could contribute to the development of anaemia." (PMID 36989322, 2023). "Interestingly, in addition to correcting anemia, EPO administration protects against ischemia-induced kidney injury." (PMID 38022248, 2023). "However, the use of HIF stabilizers or synthetic human EPO (known as rhEPO) was originally intended to treat anemia." (PMID 38203416, 2023).
anemia (continued). "However, when patients have both the predictive factors of poor response, namely, higher levels of EPO and ASXL1 mutations, alternative therapies would be recommended as the first-line therapy for anemia." (PMID 35821550, 2022). "Similarly, we found that mice fed adenine diet exhibited anemia, as it was determined by low hemoglobin, hematocrit, and serum EPO levels, compared to mice fed control diet." (PMID 35813388, 2022). "With regard to the potential EPO-producing ability of renin-producing cells, one could speculate about new therapeutic opportunities to treat anemia in patients with chronic kidney disease." (PMID 35511367, 2022). "G-CSF and EPO showed good synergistic in vivo and in vitro effects on anemia alleviation." (PMID 35250989, 2022). "Therefore, a clinical trial that studies the effect of EPO treatment in AKI patients with anemia is needed." (PMID 35279078, 2022). "While anemia appears to be a major driver of increased EPO secretion in patients with STEC-HUS, we wondered whether other mechanisms might also play a role." (PMID 36211426, 2022). "Also, one of the side effects of talazoparib is anemia, whilst evidence shows that calcitriol reduces anemia and the need for erythropoietin therapy." (PMID 36145297, 2022). "EPO level was best able to identify anemia and depleted iron stores." (PMID 35629394, 2022). "Recovery of renal function improved anemia through an increase of erythropoietin secretion, which may have contributed to the improvement in the cardiac function." (PMID 36484929, 2022). "In addition, in patients with CKD, erythropoietin production is decreased, and anemia is developed, which is one of the primary treatment goals for CKD patients." (PMID 36312236, 2022). "Importantly, uremic toxins via impaired erythropoietin synthesis contribute to the development of anemia." (PMID 36295889, 2022). "In contrast, EPO levels were not elevated at 50 weeks despite marked iron deficiency anemia, indicating that chronic renal damage and fibrosis disrupted the renal HPHE signaling axis." (PMID 35445830, 2022). "Thus, anemia in CKD results from decreased EPO production, suppression of erythroid progenitors, restricted iron availability, and shortened erythrocyte lifespan." (PMID 35751858, 2022). "However, the current clinically approved PHD inhibitors are optimized for treatment of anemia in chronic kidney disease via upregulation of EPO production in the liver and kidneys." (PMID 35852137, 2022). "ERFE is a glycoprotein hormone, which along another the erythropoietic regulator, is secreted by splenocytes and erythroblasts in response to ineffective erythropoiesis, anemia, hemorrhage, and EPO stimulation leading to the suppression of hepcidin production in hepatocytes." (PMID 36620219, 2022). "Insufficient production of erythropoietin (EPO) leads to anaemia." (PMID 35756347, 2022). "The current research point of view is that malignant changes such as anemia, electrolyte imbalance, and abnormal lipid metabolism in patients with end-stage renal disease are closely related to the decline of erythropoietin (EPO) and glomerular filtration capacity." (PMID 36466094, 2022). "BThal disease manifestations result in chronic severe anemia which stimulates the production of erythropoietin (EPO) with a consequent intensive but ineffective expansion of the BM erythroid compartment, leading to ineffective erythropoiesis (IE), altered BM homeostasis, and stress signals." (PMID 35631417, 2022). "EPO production is activated under conditions of hypoxia and anemia to accelerate RBC production." (PMID 36620219, 2022). "Although treatment of anemia and iron deficiency with subcutaneous erythropoietin and oral iron supplementation has not been shown to be beneficial, trials of intravenous iron repletion have demonstrated consistent benefits." (PMID 35508964, 2022).
anemia (continued). "Rats were exposed to 2.0 mg Cd/kg b.w. by subcutaneous injection once a week for 6 or 9 months and showed anemia with low levels of plasma EPO over time along with hypoinduction of Epo mRNA in the kidneys, which were accompanied by biochemical and histological renal tubular damage." (PMID 35445830, 2022). "“Anemia” and “rhuepo (recombinant human erythropoietin)” were early fields in uremic cardiomyopathy (Cluster ID #1 and ID #4), which are attributed to the discovery of anemia-induced cardiac injury in CKD and erythropoietin can mitigate LVH in patients with CKD." (PMID 35903671, 2022). "EPO is traditionally used in preterm neonates for the treatment of anemia of prematurity." (PMID 36699298, 2022). "The relatively high proportion of patients with cancer-induced anemia, also visible in our cohort, may require blood transfusion or other available methods of treatment (erythropoietin or iron supplementation)." (PMID 35669480, 2022). "Erythropoietin (EPO) is commonly thought to alleviate anemia in patients after radiotherapy." (PMID 36406133, 2022). "Anemia provoked by hypersplenism or the decrease of erythropoietin bone marrow stem cells due to the infiltrating storage cells could be a trigger." (PMID 36009368, 2022). "However, this mild increase seemed to diminish the response to anemia, with EPO, as well as sTfR levels remaining low, despite low SI." (PMID 35177695, 2022). "Systemic administration of EPO is used to treat adult anemia and has been discussed as a potential treatment for atrophic AMD due to its neuroprotective effects on the retina; however, there are associations between increased serum EPO and severity of CNV in AMD patients." (PMID 35884958, 2022). "Serum erythropoietin was measured in a subset of monkeys prior to treatment and found to not be significantly different from baseline, consistent with a delayed BM response to infection-induced anemia." (PMID 35811680, 2022). "The administration of EPO in cancer patients with anaemia revolutionised the treatment of this complication around 20 years ago with impressive results from a haematological perspective while simultaneously avoiding the adverse effects of blood transfusions in anaemic patients with cancer." (PMID 35626116, 2022). "Considering the posttransplant persistence of pretransplant anemia and posttransplant erythropoietin resistance, it may be reasonable to continue ESA after transplant until early PTA recovery." (PMID 35795334, 2022). "In addition, anemia occurs as a consequence of low erythropoietin response in patients with solid tumors that is, to some extent, independent of chemotherapy." (PMID 35219339, 2022). "Additionally, one of the side effects of talazoparib is anemia, whilst evidence shows that calcitriol improves anemia and lessens the requirement for erythropoietin therapy." (PMID 36145297, 2022). "Achieving guidelines goals for anemia management has been challenging in this population in large part due to the practice of addressing the erythropoietin dosing monthly while recognizing that the RBC lifespan is 90 days, creating a disconnect between prescription and outcome assessment." (PMID 35402468, 2022). "Finally, diabetes-related chronic hyperglycemia can also lead to anemia via impaired erythropoietin production." (PMID 36362486, 2022). "Other elements that have been recognized as attributing to anemia in CKD patients are erythropoietin resistance, systemic inflammation prompted by CKD and associated medical conditions, iron deficiency, higher levels of hepcidin, folate insufficiency, and cobalamin deficit." (PMID 35746954, 2022). "EPO is an erythroid growth factor necessary for erythropoiesis, the lack of which is associated with anemia." (PMID 35806113, 2022). "Anaemia is highly prevalent in end-stage renal disease patients, often non-regenerative normochromic normocytic anaemia caused by inadequate renal erythropoietin production." (PMID 36263390, 2022).
anemia (continued). "Several studies reported that vitamin D supplementation could improve anemia by increasing erythropoietin production and erythropoietin receptor expression, reducing the secretion of proinflammatory mediators, and enhancing erythropoietin sensitivity." (PMID 35370939, 2022). "In anemia cases related to ineffective erythropoiesis, the imbalance between red blood cell supply and demand still exists, in spite of tissue hypoxia and increased EPO." (PMID 36523997, 2022). "However, cHb concentrations are influenced by anaemia, decreased red blood cell (RBC) lifespan, dialysis-related RBC loss or erythropoietin treatment, which limits the semiological value of this marker." (PMID 35008998, 2022). "In adult cohorts with chronic kidney disease, scholars have found that CRP exacerbated anemia by inhibiting endogenous/exogenous erythropoietin, which may contribute to a synergic effect between inflammation and anemia on unfavorable events." (PMID 36405830, 2022). "It seems that inadequate excretion of erythropoietin (EPO) compared to the degree of anemia, reduction of erythrocytes’ survival time (<10%), inadequacy of ferric management, and direct suppression of erythropoiesis by neoplastic cells are mainly responsible for the development of ACD." (PMID 35334593, 2022). "In MF patients, disease-related anemia can be exacerbated by treatment with ruxolitinib because of myelosuppression, an adverse event that is consistent with the drug’s interference with erythropoietin signaling via JAK-STAT (especially JAK2), which is essential for erythropoiesis." (PMID 35045875, 2022). "Anemia due to insufficient production of EPO was observed in chronic Cd-intoxication of rats." (PMID 35445830, 2022). "In addition, clinical trials have reported that recombinant human EPO to treat anemia in cancer patients during chemotherapy or radiotherapy increases cancer patient mortality." (PMID 36567722, 2022). "Anemia resulting from inadequate EPO production is a common complication of CKD." (PMID 35535500, 2022). "The association between anemia and iFGF23 was independent of age, EPO, and eGFR (β = 6.56, standard error = 2.84, p = 0.021)." (PMID 35739404, 2022). "However, the cause of anemia in CKD is multifactorial and includes not only insufficient EPO production but also pro-inflammatory cytokine activation and iron deficiency, among others." (PMID 35813388, 2022). "However, one cross-sectional study on the association between serum EPO level and the formation of coronary collateral vessels found anemia to be a potent stimulator of coronary collateral vessel formation instead of serum EPO level in coronary artery disease." (PMID 35812547, 2022). "Although it is difficult to make definitive projections of how the single‐dose EPO findings from this study would translate to CKD patients with anemia and hepatic impairment on long‐term daprodustat treatment, routine monitoring of hemoglobin is expected, and doses titrated for each individual." (PMID 35355447, 2022). "Likewise, vitamin C increased hemoglobin synthesis in patients on hemodialysis with anemia refractory to erythropoietin." (PMID 35832553, 2022). "Previous studies showed that dilutional anemia and elevated erythropoietin in more severe HF might decrease hepcidin levels and nullify the effect of inflammation on hepcidin." (PMID 36578916, 2022). "Oral and intravenous iron supplementation and EPO are strategies to improve preoperative anemia." (PMID 36539891, 2022). "Nevertheless, these data indicated that the carbamylation of EPO could contribute to anaemia by preventing erythropoiesis." (PMID 35008998, 2022). "Anemia is a known complication in CKD patients due to decreased erythropoietin (EPO)." (PMID 36106212, 2022). "Anemia was found in most patients, although all were receiving erythropoietin." (PMID 35442270, 2022). "However, using erythropoietin (EPO) to treat anemia in acute kidney injury (AKI) remains controversial." (PMID 35279078, 2022).